CDKN1A (cyclin dependent kinase inhibitor 1A)
Diseases named in the same sentence as CDKN1A in open-access papers (continued):
Sharing a sentence is not in itself a finding about the gene and the disease.
cancer (continued). "The second network, involved in cancer, has MYC as the central node (score = 144.3), followed by CDKN1A (score = 119.5) and FOS (score = 118.4)." (PMID 29216278, 2017). "The well-documented cancer-related genes NOTCH1, CDKN1A, EGR1, AKT3, TNF, MMP9, and SMARCA4 are located in the center of this newly constructed subnetwork." (PMID 28500316, 2017). "Histone Deacetylase Inhibitors (HDIs) have been shown to activate silenced genes including CDKN1A, CDKN2A,SALL3, RARb2, TERT and GATA4, in the human cancer cells by active DNA demethylation of their respective promoters." (PMID 28077797, 2017). "HDIs, TSA, depsipeptide and sodium butyrate, were shown to enhance the expression of genes such as CDKN2A, CDKN1A, SALL3, RARb2, TERT and GATA4 in human cancer cell lines by active DNA demethylation of their respective promoters." (PMID 28077797, 2017). "Methylation of Cdkn1a TSS was measured via bisulfite sequencing, and methylation of a panel of cancer-related genes was quantified using methyl arrays." (PMID 28811844, 2017). "The increase in CDKN1A and γ-H2AX expression in D384 cells upon DhL exposure also indicated cell cycle arrest and DNA damage response of cancer cells, in which DhL would induce DNA repair mechanisms." (PMID 26309132, 2015). "The targeted sequencing of other cancer-related genes, including KRAS, BRAF, CDKN1A, KIT (abstract only), JAK2, FOXL2, IDH1, AKT1 and EZH2 did not reveal any pathogenic mutations." (PMID 26415226, 2015). "We selected the genes G0S2, CDKN1A and MYC as master examples for demonstrating the complex role of 1,25(OH)2D3 in the control of cellular proliferation in this cancer cell model." (PMID 24202443, 2013). "In humans, aberrant expression of CDKN1A and/or CDKN1B in various carcinomas of lung, colorectum, cervix, head and neck leads to carcinogenesis by blocking DNA synthesis and inhibiting cell growth." (PMID 23236518, 2012). "Our results show new functions for CGGBP1 in cell cycle, in regulation of expression of CDKN1A and GAS1, and provide insights into how CGGBP1 depletion overrides the redundancies of checkpoint escape mechanisms present in different cancer cells." (PMID 21733196, 2011). "STAT3 may induce genes that suppress cancer progression, such as FOXO1, p14ARF, and CDKN1A (P21), as previously reported." (PMID 41104968, 2025). "Intersecting the sets of pan-cancer compensated and toxic genes yields nine high-confidence ARGOS genes, six of which are also frequently amplified: RBM12, RBM14, SNRPA, ZBTB14, POU2F1, and CDKN1A." (PMID 39870664, 2025). "When comparing HLA-E positive with HLA-E negative cancer cells, analysis of the top 50 DEGs revealed several cell cycle-related genes that were highly expressed in HLA-E positive cancer cells, including CDKN1A, CDK4, and MDM2." (PMID 40959273, 2025). "Among the DEGs positively modulated in SCE17-exposed cells, we can highlight genes involved in cancer progression, such as FOS, JUN, and JUNB proto-oncogenes, Cyclin Dependent Kinase Inhibitor 1A (CDKN1A), and Tumor Protein 53 Inducible Nuclear Protein 1 (TP53INP1)." (PMID 41440891, 2025).
cancer (continued). "• Exertion of anticancer effects through 3 major pathways: apoptosis (BIRC3, BIRC5, caspase-8, caspase-9, and PARP1), transcriptional dysregulation in cancer (CDKN1A, CDKN1B, MMP9, MYC, JUN, and RELA), and cancer progression (caspase-3, CCND1, CTNNB1, VEGFA, and Wnt-1)." (PMID 39181121, 2025). "Adding to the activation of CDKN1A and downregulation of CDK1/CYCB1, the present data suggest a direct transcriptional dysregulation of key cell cycle and survival modulators that inhibit the proliferation capacity of cancer cells." (PMID 38166099, 2024). "In DOX-surviving proliferative cells, we found positively correlated gene pairs, for example, two senescent markers (GDF15 and CDKN1A R= 0.54) and anticorrelated gene pairs, for example, GDF15 and genes involved in cancer progression: CDC20 (R= -0.26) and BIRC5 (R= -0.17)." (PMID 39405604, 2024). "For example, BAX expression among cancer cells is lowest in upper aerodigestive lineages (UAD) and highest in fibroblast lineages; CDKN1A is lowest in blood and highest in fibroblasts; GDF15 is lowest in lymphocytes and highest in kidney; and MDM2 is lowest in thyroid lineages and highest in cervix." (PMID 36681780, 2023). "Similarly, our integrated analysis identified CDKN1A and FANCD2 as the key genes of STARD14 playing a cancer promoting role in LUAD." (PMID 37790851, 2023). "In differentiated cancer cells, NR5A2 promotes cell proliferation by inhibiting CDKN1A." (PMID 38012687, 2023). "Finally combined with survival analysis identified CDKN1A and FANCD2 as the key genes of STARD14 playing a cancer promoting role in LUAD." (PMID 37790851, 2023). "Statins have been shown to induce p21 (also termed CDKN1A) that plays an important role in cell cycle inhibition to antagonize RAS-dependent signaling pathways or to downregulate BCL-2 expression in cancer cell lines and, thus, affect apoptosis." (PMID 35406471, 2022). "We performed RT-qPCR and confirmed the differential expression of several cancer driver genes: increased mRNA expression of oncogenes MYC and PIK3CG, as well as decreased expression of tumor suppressor genes CDKN1A and EPHA2, was observed in the H2BE76K mutant cells." (PMID 33548228, 2021). "Although IRF9 is not reported to influence cell cycle progression in cancer cells, the observed changes in CDKN1A expression alterations encourage research focused in this field." (PMID 33430083, 2021). "The three clusters generated contained genes or proteins involved in apoptosis (BIRC3, BIRC5, PARP1, CASP8, and CASP9), transcriptional dysregulation in cancer (CDKN1B, RELA, CDKN1A, MYC, JUN, and MMP9), and cancer progression (CCND1, CASP3, CTNNB1, WNT1, and VEGFA) pathways." (PMID 34836311, 2021).
cancer (continued). "The activation of CDKN1A gene expression induced by RNA may have a significant potential for the treatment of HCC and other cancers." (PMID 34095224, 2021). "The combined analysis of RNA-seq and ChIP-seq for H2A.Z showed downstream gene regulation to mainly occur via the transcriptional misregulation in the cancer pathway, its target genes mainly including TCF3 CDK14, JUP, SPINT1, CDKN1A, and IGF1, each of which corresponded to different cell phenotypes." (PMID 34120148, 2021). "Moreover, using PPI networks, key cancer regulators such as MYC, VEGFA, AKT1, CDKN1A, RHOA, and PTEN are identified." (PMID 33281862, 2020). "In human cancers, MYC and the transcription activator MIZ1 (MYC-interacting zinc-finger protein 1 [ZBTB17]) can form a protein complex that represses the expression of MIZ1 target genes, most notably cyclin-dependent kinase inhibitor genes such as CDKN1A." (PMID 32407433, 2020). "Notably, the expression of the MIZ1 target genes Cdkn1a, Cdkn2a, and Cdkn2b, known to be repressed by MYC–MIZ1 complexes in cancer cells, were also similar between the LZ of MycVD and MycWT." (PMID 32407433, 2020). "Since various factors are involved in regulations of CDKN1A and BAX genes respectively, the effect(s) of TSPX on these genes could potentially be minimized by other factors and/or cancer heterogeneity." (PMID 30863497, 2019). "Moreover, reduced EZH2 led to significantly reduced binding of LSD1, HDAC1, and DNMT1 to promoter regions of CDH1, CDKN1A, NEUROD1, and TUBB3, in agreement with increased transcription of these genes in cancer cells after EZH2 knockdown." (PMID 31130994, 2019). "RXRA, CDKN1A, and RHOA are the members of pathways in cancer." (PMID 29738475, 2018). "From the analysis of GBM dataset, we could find functional evidences of four targets including CDKN1A, MTAP, KIT and ATM among top 20 ranked miRNA-mRNA interaction pairs have been reported in GBM cancer." (PMID 25079112, 2014). "Importantly, we detected increased mRNA half-lives for cancer-related transcripts such as CCNA2, CCNB2 and CDKN1A that were previously shown to be stabilized by ELAVL1." (PMID 24417896, 2014). "We examined whether the epigenetic silencing of CDKN1A by MBD3 and FBI-1 that we observed in various cancer and immortalized cells could also be possible in primary human cells such as HDFn cells." (PMID 23658227, 2013). "It has been reported that the decreased expression of miR-92 may decrease cancer cell proliferation and increase the levels of PTEN, BCL2L11 and CDKN1A expression." (PMID 24137349, 2013). "Because kaempferol sensitizes OVCAR-3 cancer cells' response to cisplatin treatment, the effect on gene expression by cisplatin and/or kaempferol was further evaluated by analyzing mRNA levels of ABCC1, ABCC5, ABCC6, NFκB1, cMyc and CDKN1A genes." (PMID 20459793, 2010).
cancer (continued). "Its ability to stabilize specific mRNAs like p21 (CDKN1A) highlights a sophisticated layer of gene regulation that integrates the NPC with the core components of cell cycle control and apoptosis, offering insights into novel cancer therapeutic strategies to prevent HCC progression." (PMID 39000572, 2024). "Stem cell renewal and differentiation rely on the coordination between cell cycle progression and exit, and it is not surprising that CDKN1A/p21, as a regulator of those functions, plays an important role in the determination of stem cell fate, especially in cancer stem cells." (PMID 38139316, 2023). "The expression of CDKN1A is related to the progression of various cancers, and it can be initiated by oncogenes, tumor suppressors, inflammatory cytokines, etc., and can inhibit cell proliferation by binding to CDKS, thus inhibiting the growth function of cancer cells." (PMID 35847900, 2022). "Using qPCR assay for known genes modulated NT157 in other cancer models, we identified that NT157 decreased expression of oncogenes BCL2, CCND1, MYB, and MYC and increased genes related to cellular stress and apoptosis, JUN, BBC3, CDKN1A, CDKN1B, FOS, and EGR1 (all p < 0.05)." (PMID 36224313, 2022). "The promoter of the gene for cyclin dependent kinase inhibitor 1A, CDKN1A anti-sense DNA damage-activated RNA (PANDAR; NCBI gene ID: 101154753) is a noncoding RNA located on chromosome 6p21.2, whose abnormal expression is involved in the pathogeneses of various cancers." (PMID 37551364, 2021). "miR-133a-3p may have a key role in mechanisms that lead to either cancer (target genes CDKN1A, and CCND1) or non-cancerous (target gene EDN1, and CXCL2) conditions secondary to smoking." (PMID 34440025, 2021). "CDKN1A has been described previously as an inhibitor of cyclin-dependent kinase and plays an important regulatory role in cell proliferation, differentiation and senescence, but its function in the development of different cancers is not consistent." (PMID 30497491, 2018). "CDKN1A is well known for mediating cell cycle arrest in cancer cells; however, the in-depth mechanism of CDKN1A in chemoresistance is unclear, and the role of CDKN1A in the process of chemoresistance is not consistent in different cancers." (PMID 30497491, 2018). "However, to promote cancer activity, they also target different genes including C/EBPβ, FOXO1, NFI-A, STAT5A, ARTN, FBXW7, and SEPT6 (for miR-223) and FUS1, RhoC, PTEN, CDKN1A, TGFβR2, and NRF2 (for miR-93)." (PMID 26273679, 2015). "Additionally, the IL-6- and/or MYC-driven mouse models of human BL and MM used in this study may lend themselves to the biological validation of CDKN1A and FANCD2 as molecular targets for new approaches to cancer therapy and prevention." (PMID 25838973, 2015). "In addition to these peptidomimetics of CDKN1A, SDCs, called 'dimerizers', that induce or stabilize CDK2/cyclin A/CDKN1A protein complex could potentially lead to treatments for cancer." (PMID 17705877, 2007). "In addition, we found that acetylation of H2A.Z in HCC could change the chromatin status and promote the transcription of downstream genes, including TCF3, CDK14, JUP, SPINT1, CDKN1A, and IGF1, which are important regulatory molecules in the cancer misregulation pathway." (PMID 34120148, 2021).
cancer (continued). "Thus, under the cooperation of TGFβR2, CDKN1A and RAD21, the inhibition of DNA synthesis and the repair of DNA damage result in allowing cells to survival with the burden of potentially lethal cisplatin-induced cytotoxicity, and then cancer cells become resistant to cisplatin." (PMID 26482648, 2015). "Our published findings indicate that FXR1 helps cancer cells bypass cellular senescence by stabilizing the non-coding telomerase RNA component (TERC) and destabilizing CDKN1A (p21) to promote cell growth." (PMID 38709899, 2024). "At the level of all cancers, we noticed that CBX2 and CDKN1A exhibited a negative trend, strengthening CBX2’s ability to regulate the cell cycle." (PMID 37980163, 2023). "Positive correlation with cancer-promoting genes BCL2, BCLxL, HIF1A, VEGFA, ACTA2, CCL2, PTGS2, and CDKN1A, but not Ki67, was demonstrated, particularly for ILs’ receptors." (PMID 32512917, 2020). "For example, for the two miRNA pairs that both are members of the miR-15 family (miR-15a/b), the top three possible co-functional targets for the non-cancer diseases are IFNG, MTHFR, RARB, while for cancers are BCL2, CDKN1A and CCND1." (PMID 28340554, 2017). "In contrast, DOX-untreated cancer cells showed no notable “blocks” of co-expression patterns for the analyzed genes, despite the presence of correlation between single marker genes such as the senescence markers GDF15 and CDKN1A." (PMID 39405604, 2024). "Recent studies show that DINO is silenced in human cancers, and some evidence shows that a region of the DINO/CDKN1A locus is hypermethylated, leading to the silencing of DINO but not CDKN1A." (PMID 35774512, 2022). "However this is not incongruous with Cdkn1a over-expression in the MIN-Os, as p21 is often over-expressed in human cancer, and more studies have shown p21 as a modulator of cell proliferation, rather than inhibitor." (PMID 17147824, 2006). "Moreover, the expression of CDKN1A and senescence gene FN1 with the lack of expression of PCNA can trigger the G2 arrest or the stress-induced premature senescence (SIPS) found in a previous cancer study." (PMID 38328306, 2023). "While no studies have previously been published in other cancer cell lines for transient overexpression of TBX4 and 5, numerous studies have shown that transient overexpression of TBX2 or TBX3 does specifically affect senescence by targeting the tumor suppressor gene CDKN1A and B, and CDKN2A." (PMID 30425966, 2018).